CD4 (CD4 molecule)
Diseases named in the same sentence as CD4 in open-access papers (continued):
Sharing a sentence is not in itself a finding about the gene and the disease.
peritonsillar abscess (1 paper, 2017). An abscess that develops in the space surrounding one or both palatine tonsils. "T-cells from patients with CT, in average, expressed higher PD-1 levels (in PD-1(+)) on their surface than T-cells from peritonsillar abscess (PD-1(+) in CD4(+) T-cells p = 0.026)." (PMID 28877231, 2017).
pernicious anemia (1 paper, 2019). Megaloblastic anemia caused by vitamin B-12 deficiency due to impaired absorption. "For the first time we provide evidence that gastric mucosa of pernicious anemia patients harbour a high proportion (20%) of autoreactive activated CD4+ T-cell clones that specifically recognize intrinsic factor." (PMID 31080562, 2019).
pharyngitis (1 paper, 2022). Inflammation of the throat most often caused by viral and bacterial infections. "Collectively, our data support a role for specific subsets of dendritic cells, monocytes, CD4+ T cells and γδTCR + Vδ2+ T cells in acute S. pyogenes pharyngitis." (PMID 35140232, 2022). "In contrast, CD4+ and CD8+ T cells did not upregulate CD69 expression during acute pharyngitis." (PMID 35140232, 2022).
Photophobia (1 paper, 2012). Excessive sensitivity to light with the sensation of discomfort or pain in the eyes due to exposure to bright light. "At bivariate analysis the presence of headache, neck pain, convulsions, photophobia, meningeal irritation signs, WHO stage III and IV, altered mentation and CD4 counts of less than 50 cells/mm3 were significantly associated with cryptococcal antigenemia." (PMID 22417404, 2012).
photosensitive (1 paper, 2025). "Collectively, these results indicate that type I interferon selectively enhances the cytotoxic program and effector function of Th1 CD4+ T cells, a mechanism that likely contributes to tissue damage in photosensitive skin disease." (PMID 40894544, 2025).
pituitary tumor (1 paper, 2023). A benign or malignant neoplasm affecting the pituitary gland. "The role of lymphocytic infiltrate in pituitary tumors has been described, including CD3+, CD45+, cytotoxic CD8+ T cells, and CD4+ T helper, in particular in functioning pituitary tumors, and, to a lesser extent, also B cells, neutrophils, and mast cells." (PMID 37958702, 2023). "In pituitary tumors with a Ki-67 ≥ 3%, lower CD8:CD4 and CD8:FOXP3 T cell ratios and higher levels of macrophages, T helper, FOXP3+, and B cells were reported." (PMID 37958702, 2023). "The pituitary tumors characterized by elevated expression of PD-L1 presented prevalent immune infiltrates of CD4+, CD8+, and FOXP3+ T cells, highlighting the ability of pituitary tumor-infiltrating immune cells to modulate the expression of immune checkpoint regulators." (PMID 37958702, 2023).
plasma cell dyscrasias (1 paper, 2025). "In our study of samples from patients with plasma cell dyscrasias, we found little expression of Syk in CD4+ T cells but abundant levels in monocytes." (PMID 40539671, 2025).
POEMS syndrome (1 paper, 2022). POEMS syndrome is a paraneoplastic syndrome characterized by polyradiculoneuropathy (P), organomegaly (O), endocrinopathy (E), clonal plasma cell disorder (M), and skin changes (S). "A recent analysis revealed that double-positive T cells with effector memory phenotype and PD-1+–exhausted CD4+ T cells were expanded and naive CD4+ T cells were decreased in the BM of individuals with POEMS syndrome." (PMID 36129760, 2022).
poisoning (1 paper, 2025). A condition or physical state produced by the ingestion, injection, inhalation of or exposure to a deleterious agent. "In summary, we found the lymphocyte count, neutrophil count, and CD4+/CD8+ T cell ratio are positively correlated with mortality in paraquat poisoning patients, while the NK cell percentage is negatively correlated with mortality." (PMID 39976478, 2025).
poliovirus infection (1 paper, 2019). An disease or disorder caused by infection with Enterovirus C. "However, clearance of poliovirus infection by both CD4+ve and CD8+ve cytotoxic T lymphocytes by secretion of IFNγ has been shown by some earlier studies." (PMID 31396204, 2019).
polyglucosan body myopathy (1 paper, 2020). "Similarly, we also analyzed CD4+ T‐cells from a recently described female patient suffering from polyglucosan body myopathy (PBM) due to a mutation in the RBCK‐1 gene." (PMID 32319705, 2020).
Pompe Disease (1 paper, 2023). "In the GAA−/− 129SVE mouse model of Pompe Disease, robust IgG1 antibody generation against human rhGAA is driven by immunodominant CD4+ Th2 cell epitopes, and these affected mice with high IgG antibody titers ultimately die from IgE-mediated anaphylaxis." (PMID 38250073, 2023).
postherpetic neuralgia (1 paper, 2025). "The results of multi-factor Logistic regression analysis showed that age, CD4+/CD8+ ratio, Treg cell ratio, IL-6, TNF-α, and IL-10 were the independent risk factors for postherpetic neuralgia (p < 0.05)." (PMID 40606470, 2025).
pregnancy-induced hypertension (1 paper, 2025). "In women with pregnancy-induced hypertension, a higher percentage of Th17 cells (CD4+ IL-17+) suggests the involvement of this subpopulation in the generalized inflammatory response in the circulation." (PMID 41156157, 2025).
Proteinuria (1 paper, 2018). Increased levels of protein in the urine. "Proteinuria could serve as a noninvasive screening tool, but the combination of proteinuria, leukocyturia, hematuria, and TLC serves as a better substitute marker for CD4 count in monitoring the disease progression among HIV patients in low-resource communities." (PMID 29606987, 2018).
prurigo (1 paper, 2023). A name applied to several itchy skin eruptions of unknown cause. "Another important skin problem observed in our study was prurigo, which was present in 13 (5.65%) cases and associated with a mean CD4 count of 106 cells/mm3." (PMID 37581910, 2023).
Pulmonary hemorrhage (1 paper, 2020). Pulmonary hemorrhage is a bleeding within the lungs. "Similarly, pathological observation showed that lesions such as pulmonary hemorrhage and inflammatory cell infiltration were significantly reduced after injection of CD4+ T cells." (PMID 33552056, 2020).
reactive disorder of (1 paper, 2022). "More research is warranted to clarify whether CD4+ T-LGLL is a true hematological malignancy or a reactive disorder of the immune system as clonal T cell proliferations and somatic mutations are also observed in healthy controls and non-malignant diseases." (PMID 35210405, 2022).
respiratory distress syndrome (1 paper, 2024). "This immunocompromised PLWH, with a CD4 count of less than 200 cells/mm3 and high HIV viremia, died of COVID-19 pneumonia with respiratory distress syndrome, six months after receiving the mRNA-1273 booster." (PMID 39636838, 2024).
restrictive lung disease (1 paper, 2025). "The PFT revealed restrictive lung disease in 38.5% and reduced diffusion capacity in 68%, 19.2% showed a pathological BAL cell pattern predominantly consisting of CD4+ T‐cells." (PMID 40263177, 2025).
retinal vasculitis (1 paper, 2025). Inflammation of the retinal vasculature with various causes including infectious disease; lupus erythematosus, systemic; multiple sclerosis; behcet syndrome; and chorioretinitis. "Previous studies have suggested that T follicular helper (Tfh) cells, a recently identified subset of CD4+ T cells, play a role in retinal vasculitis associated with DR." (PMID 40176795, 2025).
rhabdomyolysis (1 paper, 2022). Necrosis or disintegration of skeletal muscle often followed by myoglobinuria. "Upon further characterization of the lymphoid populations, we determined that rhabdomyolysis was associated with a temporal increase in CD4+, CD8+, and regulatory T cells, with maximal abundance identified on the day 28 after injury." (PMID 36160140, 2022).
RSV bronchiolitis (1 paper, 2020). "We demonstrated lower TNF‐α production by in vitro stimulated CD4+ T cells during severe RSV bronchiolitis in children that subsequently developed recurrent wheezing, compared with children with no subsequent wheeze." (PMID 31901157, 2020). "We demonstrated lower tumor necrosis factor‐α production by in vitro stimulated CD4+ T cells during severe RSV bronchiolitis in children that subsequently developed recurrent wheezing, compared with children with no subsequent wheeze." (PMID 31901157, 2020). "In summary, we have demonstrated lower TNF‐α production by in vitro stimulated CD4+ T cells during severe RSV bronchiolitis in children who subsequently developed recurrent wheezing in the first 3 years of life." (PMID 31901157, 2020). "The purpose of this study was to evaluate a putative relationship between circulating Foxp3+ Tregs and cytokine production of in vitro activated CD4+ T cells in infants with acute severe RSV bronchiolitis and the development of recurrent wheezing in the first 3 years of life." (PMID 31901157, 2020). "The slight reduction in both Treg (CD4+CD25hiFoxp3hi) and activated CD4+CD25+Foxp3+ T cells could be due to a recruitment of these cells to airway, apoptosis or their plasticity in these children with acute severe RSV bronchiolitis." (PMID 31901157, 2020). "We also did not assess baseline CD4+ cell phenotype and function before RSV bronchiolitis as this was not a birth cohort." (PMID 31901157, 2020).
salivary gland cancer (1 paper, 2023). A primary or metastatic malignant neoplasm that affects the major or minor salivary glands. "A selected number of immunohistochemical markers related to TILs (CD3, CD4, CD68, and FOXP3) and TAMs (CD68 and CD163) were investigated on major salivary gland cancers." (PMID 37465638, 2023).
scleritis (1 paper, 2021). Inflammation of the sclera. "In sclera of the CIA-scleritis model, infiltration of CD4+, CD8+, CD11b+, CD11c+, B220+ and CD138+ cells was observed from 3 weeks after the second immunisation with CII." (PMID 35008766, 2021).
scoliosis (1 paper, 2025). A congenital or acquired spinal deformity characterized by lateral curvature of the spine. "CD45RA on naive CD4+ T cell could decrease the risk of scoliosis." (PMID 40270514, 2025).
skin toxicity (1 paper, 2025). "An inflammatory infiltrate composed of CD4+ and CD8+ T cells was identified as a contributing factor to EV-associated skin toxicity based on histopathological data from prior studies, suggesting that it shares pathologic features with ICI-associated skin toxicity." (PMID 40926943, 2025).
somatotrophinomas (1 paper, 2020). "Within NF-PitNETs, increased amounts of infiltrating CD4+ and FOXP3+ T cells were associated with bigger vessels, while in somatotrophinomas larger vessels correlated with more macrophages." (PMID 32946040, 2020).
spinal tuberculosis (1 paper, 2024). "CD4+ and CD8+ T cells were detected in HIV-negative spinal tuberculosis tissue sections, along with a population of CD68-positive macrophages in the tissue microenvironment." (PMID 38572322, 2024).
spondylitis (1 paper, 2018). The inflammation of a vertebra. "Especially, when using PSMα3-induced tDCs to prime iTregs in allogenic and autologous settings of CD4+ T cells from spondylitis patients." (PMID 30555457, 2018).
squamous papilloma (1 paper, 2019). A benign epithelial neoplasm characterized by a papillary growth pattern and a proliferation of neoplastic squamous cells without morphologic evidence of malignancy. "The lowest proportion of CD4+ cells was in squamous papilloma (7.4%)." (PMID 31718115, 2019).
STING-associated vasculopathy with onset in infancy (1 paper, 2023). "STING is able to activate the NF–κB pathway and also to determine a progressive CD4+CD8+ T lymphocytopenia, similar to what occurs in STING-associated vasculopathy with onset in infancy (SAVI) syndromes." (PMID 36836679, 2023).
submandibular lymphadenitis (1 paper, 2022). "A year and a half later, she was referred with submandibular lymphadenitis and underwent immunologic work-up which revealed high inflammatory indices, a slight reduction in numbers of CD3 + and CD4 + cells as well as elevated CD16/56 + cell count and hyperimmunoglobulinemia." (PMID 36397171, 2022).
substance-related disorder (1 paper, 2023). A category of psychiatric disorders which include disorders related to the taking of a drug of abuse (including alcohol, prescribed medications and recreational drugs). "Additionally, 14% had an HIV-related hospitalization, with significant risk factors including prior psychiatric outpatient visits, alcohol- and substance-related disorder diagnoses, female sex, older age, CD4 count < 500 cells/uL, and detectable viral load." (PMID 37084105, 2023). "In terms of HIV-related hospitalization, consistent with hypotheses, results suggest a higher number of previous outpatient psychiatric visits, a past diagnosis of alcohol- or substance-related disorders, and CD4 count < 500 cells/uL or a detectable viral load were associated with increased risk." (PMID 37084105, 2023).
sympathetic ophthalmia (1 paper, 2023). Sympathetic ophthalmia (SO) is a bilateral granulomatous anterior uveitis usually occurring within the three months following trauma or a surgical procedure involving one eye. "The downregulation of miR-182 was also detected in CD4+ T cells of EAU mice and in the ocular tissues and CD4+ T cells of human patients with sympathetic ophthalmia (SO)." (PMID 36891312, 2023).
syringoma (1 paper, 2025). A benign sweat gland neoplasm usually affecting the lower eyelids and upper cheeks. "While the pathophysiology of eruptive syringomas is not completely understood, immunohistochemical staining of syringoma tissue has shown an infiltrate of CD4+ and CD8+ T cells surrounding the sweat ducts." (PMID 40099177, 2025).
Takotsubo syndrome (1 paper, 2021). "However, the elevated IL-2 and IL-4 levels in Takotsubo syndrome point towards activation of circulating CD4 and CD8 T cells as these are the primary source of these interleukins." (PMID 34095448, 2021).
teratocarcinoma (1 paper, 2016). A germ cell tumor characterized by the presence of an embryonal carcinoma component and a teratoma component. "In contrast, temporarily immunosuppressed allogeneic mice, following cessation of tacrolimus injection displayed diminished progression of the teratocarcinoma, accompanied by an accumulation of CD4/CD8-positive T cells, and finally achieved complete elimination of the teratocarcinoma." (PMID 26763872, 2016).
Theileriosis (1 paper, 2019). "Theileriosis does not affect hematological profile except for hemoglobin level; however, it generally promotes CD4+ depletion." (PMID 31749567, 2019).
Thyroid adenoma (1 paper, 2020). The presence of a adenoma of the thyroid gland. "• Compared with patients with thyroid adenoma, PTC patients have significantly increased CD4+ CD25+ regulatory T cells in the peripheral blood." (PMID 33193087, 2020).
Toxocara infection (1 paper, 2023). "The mean CD4+ count in HIV-infected individuals with positive toxocariasis serology was 255.1 ± 21.6 cells/μL." (PMID 37138234, 2023). "This could possibly be due to that although all groups are equally susceptible to toxocariasis, هn patients with CD4+ more than 500 cells/μL immune system is not yet compromised thus they have more ability to clear out the parasites before they become established in the body." (PMID 37138234, 2023). "A serological study has demonstrated that the prevalence of toxocariasis was higher (although not significant) in HIV1+ patients with CD4+ count between 200 and 500 cells/μL." (PMID 37138234, 2023).
Trematode Infections (1 paper, 2013). Infections caused by infestation with worms of the class Trematoda. "In summary, alongside its role in controlling CD4+ Teff-cell responses, ICOS co-stimulation promotes the expansion and maintenance of Foxp3+ Treg cells in both nematode and trematode infections." (PMID 23319295, 2013).
Trichiasis (1 paper, 2017). Inversion and rubbing of the eyelashes against the globe of the eye. "In peripheral blood from adults with trichiasis and controls that were stimulated ex-vivo with C. trachomatis antigens, NK cells and to a lesser extent CD8+ T cells were the major sources of IFNγ with <50% of the IFNγ produced by CD4+ T cells." (PMID 28966918, 2017).
Ureaplasma infection (1 paper, 2020). "Our result showed increased intestinal MPO, CD4, and TLRs in response to such prenatal inflammation, which are similar to those that resulted from Ureaplasma infection in sheep model, suggesting common underlying mechanisms." (PMID 32265914, 2020).
vascular tumor (1 paper, 2021). "Based on LSH, CD4 expression was significantly associated with tumor location (P=0.045), tumor differentiation (P=0.007), vascular tumor thrombus (P=0.008), postoperative chemoradiotherapy (P=0.017), and CDX2 expression (P=0.011) in PDAC patients." (PMID 34367978, 2021). "Based on SSH, CD4 expression was significantly correlated with tumor differentiation (P=0.001), whereas CD15 was significantly associated with N stage (P=0.048), the number of PDAC patients with total lymph node metastases (P=0.029) and vascular tumor thrombus (P=0.044)." (PMID 34367978, 2021).
ventricular dilation (1 paper, 2020). "Similarly, another study has supported that ablation of CD4+ T-cells by 200 μg of the lytic GK1.5 monoclonal antibody reduced left ventricular remodeling and prevented left ventricular dilation at 8 weeks after MI 11, suggesting a detrimental role of CD4+ T-cells during adult heart repair." (PMID 32724455, 2020).
Vertigo (1 paper, 2011). An abnormal sensation of spinning while the body is actually stationary. "Monitoring the CD4+ and CD8+ T lymphocytes during the spells of vertigo could help to define AIED and MD." (PMID 22053211, 2011).
Vitamin D (1 paper, 2014). "Vitamin D insufficiency did not affect total lung or bronchoalveolar lavage (BAL) cells, but did result in a significant increase in pulmonary CD3+CD4+T1ST2+ Th2 cells and a reduction in CD4+IL-10+ T regulatory cells." (PMID 24943330, 2014).
vulvar lichen sclerosus (1 paper, 2017). A chronic inflammatory disorder of unknown etiology that affects the vulva.
WHIM syndrome (1 paper, 2024). "It was recently reported that CXCR4 GOF mutations lead to a more severe depression of circulating CD8+ T-cell counts compared with CD4+ T cells in patients with WHIM syndrome and in a WHIM mouse model." (PMID 39588369, 2024).
X-linked lymphoproliferative disease (1 paper, 2016). X-linked lymphoproliferative disease is a hereditary immunodeficiency characterized, in the majority of cases, by an inadequate immune response to infection with the Epstein-Barr virus (EBV). "In fact, lack of IL-10 production by CD4+ T helper cells in X-linked lymphoproliferative disease (XLP) patients impaired the development of B cell responses." (PMID 27463374, 2016).